IFIT5 (interferon induced protein with tetratricopeptide repeats 5)
Description:
Interferon-induced RNA-binding protein involved in the human innate immune response. Has a broad and adaptable RNA structure recognition important for RNA recognition specificity in antiviral defense. Binds precursor and processed tRNAs as well as poly-U-tailed tRNA fragments. Specifically binds single-stranded RNA bearing a 5'-triphosphate group (PPP-RNA), thereby acting as a sensor of viral single-stranded RNAs. Single-stranded PPP-RNAs, which lack 2'-O-methylation of the 5' cap and bear a 5'-triphosphate group instead, are specific from viruses, providing a molecular signature to distinguish between self and non-self mRNAs by the host during viral infection. Directly binds PPP-RNA in a non-sequence-specific manner. Also recognizes and selectively binds AT-rich dsDNA. Additionally, as a mediator in innate immunity, positively regulates IKK-NFKB signaling by sinergizing the recruitment of IKK to MAP3K7.
Synonyms: P58; ISG58; RI58
Tractability: Antibody: its Gene Ontology location is reachable by antibodies, with high confidence; the Human Protein Atlas places it where antibodies can reach. PROTAC: ubiquitination databases record sites on it; its protein half-life has been measured.
Gene: Protein-coding gene on chromosome 10 (89,414,568 to 89,421,605, forward strand). Ensembl gene ENSG00000152778.
Subcellular location: Cell projection, ruffle membrane
Subcellular location (Human Protein Atlas): Plasma membrane
Pathways (Reactome):
Immune System: Interferon alpha/beta signaling
Gene Ontology:
Molecular function: double-stranded DNA binding; poly(U) RNA binding; protein binding; RNA binding; RNA cap binding; single-stranded RNA binding; tRNA binding
Biological process: defense response to virus; negative regulation of viral genome replication; positive regulation of canonical NF-kappaB signal transduction; antiviral innate immune response; cellular response to cytokine stimulus
Cellular component: actin cytoskeleton; apical part of cell; IkappaB kinase complex; plasma membrane; ruffle membrane; cytosol
Genetic constraint (gnomAD): Loss-of-function variants: 2 observed, 6.31 expected, observed/expected ratio (o/e) 0.32, 90% interval 0.13 to 1. That is too few expected variants to judge how well the gene tolerates losing a copy. Missense variants: 518 observed, 585.75 expected, observed/expected ratio (o/e) 0.88, 90% interval 0.82 to 0.95. Synonymous variants: 204 observed, 215.32 expected, observed/expected ratio (o/e) 0.95, 90% interval 0.84 to 1.06.
Homologues: Orthologues: chimpanzee IFIT5 (99% identical), macaque IFIT5 (98% identical), pig IFIT5 (93% identical), dog IFIT5 (93% identical), guinea pig IFIT5 (73% identical), tropical clawed frog ifit5l (42% identical), tropical clawed frog ifit5 (39% identical), tropical clawed frog ifit1b (37% identical), zebrafish ifit10 (34% identical), zebrafish ifit12 (31% identical), zebrafish ifit11 (31% identical), zebrafish ifit8 (27% identical), and 3 more. Paralogues in human: IFIT1 (55% identical), IFIT1B (54% identical), IFIT2 (43% identical), IFIT3 (42% identical).
Diseases named in the same sentence as IFIT5 in open-access papers:
IFIT5 is named in the same sentence as 39 diseases in open-access papers, as found by Europe PMC text mining. Sharing a sentence is not in itself a finding about the gene and the disease. The quoted sentences say what the papers report.
viral infection (26 papers, 2013 to 2025). "Network analysis of miRNA-150 in viral infections identified an association with a key interferon pathway member, interferon-induced protein with tetratricopeptide repeats 5 (IFIT5)." (PMID 30619110, 2018). "The IFIT family is comprised of four proteins in humans (IFIT1, IFIT2, IFIT3 and IFIT5) which are all located on chromosome 10q23 and induced via IFNs, viral infection or PAMP recognition." (PMID 38440728, 2024). "In other host–viral models, it has been observed that IFIT5 induces innate responses effective against viral infections." (PMID 38675946, 2024). "Hsa-miR-150-5p was linked to the greatest number of mRNA targets (sixteen), including SOCS1, SAMD4A, and IFIT5, which were part of previously published gene expression signatures for viral infection." (PMID 30619110, 2018). "Amongst all known members of the family, IFIT1 and IFIT5 are highly responsive both at the transcription and translation levels to diverse cellular stresses including those induced by dsRNA, virus infections and lipopolysaccharides." (PMID 29717152, 2018). "Human IFIT5 plays a crucial role in the host innate immune response during viral infection." (PMID 31921891, 2019). "This biphasic expression of IFIT5 after virus infection was repeatedly observed in chicken cells." (PMID 29717152, 2018). "IFIT5, a member of the IFIT1 family, can be activated under stress conditions including virus infection, the production of type I interferon, and lipopolysaccharides stimulation." (PMID 35237223, 2021). "Interferon-induced protein with tetratricopeptide repeats 5 (IFIT5) and IFIT1 recognize ssRNA carrying a 5′-triphosphate (5′-ppp) with TPR domain, protecting cells from viral infection." (PMID 35006471, 2021). "Consistent up-regulation of IFIT5 in the spleen of all chickens challenged with virulent and non-virulent NDV indicates critical role of this gene in splenic immune response to viral infections." (PMID 34475461, 2021). "IFIT5 is a member of the IFIT family, which can be triggered by viral infection and enhances the antiviral response by promoting IRF3- and NF-κB-mediated gene expression." (PMID 31865850, 2020). "We cloned chicken MX1, IFI6, IFIT5, RSAD2, and OASL into eukaryotic expression vector and evaluated their effects on virus infection in DF1 cells." (PMID 32183248, 2020). "IFNα and IFNγ, two types of antiviral cytokines, were also up-regulated after viral infection, activating the JAK-STAT signaling pathways and inducing the transcription of ISGs, including Mx, OASL2, GBP, IFIT5, and TRIM25." (PMID 27916934, 2016). "IFIT-1, IFIT-2, IFIT-3, and IFIT-5, which were found to be the most down-regulated genes in LBW newborns, are induced in response to type I and type II IFNs against viral infections." (PMID 23626859, 2013). "IFIT5 is a factor in HCV entry, HCLS1 is a newly identified transcription regulator, and RSAD2 and IFIT5 are ISGs that have been shown to be critically important to resistance to viral infection, including influenza virus, HIV-1, and other viruses." (PMID 37896995, 2023). "It is worth pointing out that only one gene was commonly differentially expressed in all four infections, namely, interferon-induced protein with tetratricopeptide repeats 5 (IFIT5), a well-known anti-viral gene that is crucial for the innate immune response against viral infections in chickens." (PMID 34835129, 2021). "In the upregulated genes in both chMDA5 and poly(I:C) groups, many genes were ISGs, such as MX1, IFI6, IFIT5, RSAD2, OASL, and, CMPK2, which suggested that these genes might play important roles in restricting virus infection in chicken." (PMID 32183248, 2020). "In conclusion, using proteomic analysis we found that the DEPs SPP1, IFIT5, ISG15, VCL, and SDC1 are significantly changed in PSV-infected PK-15 cells, suggesting that these proteins may be closely related to viral infection." (PMID 32575635, 2020).
viral infection (continued). "IFIT (IFN-induced protein with tetratricopeptide repeats (TPRs))-family proteins contain four members in humans, namely IFIT1 (ISG56), IFIT2 (ISG54), IFIT3 (ISG60) and IFIT5 (ISG58), and are induced to high levels in response to IFN signaling and/or viral infections." (PMID 29215570, 2017). "Interestingly, only minor to moderate reduction in the induction of IRF7, IRF1, VIPERIN, IFIT5, and CMPK2 was observed at 24 hpi, probably reflecting the involvement of IFN-independent mechanisms in regulating the induction of these genes at late stages of the viral infection cycle." (PMID 35891486, 2022).
prostate carcinoma (10 papers, 2019 to 2025). A carcinoma that arises from epithelial cells of the prostate gland. "A pro-oncogenic role of IFIT5 was suggested in prostate cancer, where induction of IFIT5, through miRNA processing mechanisms, promoted EMT, cell invasiveness and lung metastases in vivo." (PMID 40564154, 2025). "IFIT5 autoantibodies were upregulated in plasma samples of prostate cancer patients compared to healthy control and thus proposed to be a potential diagnostic modality in this disease." (PMID 40564154, 2025). "A similar effect is seen in prostate cancer, where IFIT5 expression induced by IFNγ treatment results in the inhibition of miR-363, which is another negative regulator of EMT." (PMID 36851555, 2023). "IFN-γ induced cancer invasiveness in prostate cancer via transcription of IFN-induced tetratricopeptide repeat 5 (IFIT5)." (PMID 35747815, 2022). "Some previous studies have indicated that IFIT5 was high-expressed and negatively correlated with the prognosis in renal cell carcinoma, bladder cancer, and prostate cancer patients." (PMID 33251144, 2020). "Our recent data unveil that IFIT5 is a novel oncogene in prostate cancer by eliciting EMT via miR processing." (PMID 31164632, 2019). "IFIT5 is involved in the degradation of miR-363 and can form a complex with miR-101 and miR-128 to promote prostate cancer progression by inducing EMT." (PMID 31921891, 2019). "Recent research has shown that IFIT5 promoted the progression of various cancers, including renal cancer, prostate cancer, and bladder cancer." (PMID 31921891, 2019). "IFIT5 induces epithelial–mesenchymal transition (EMT) in prostate cancer cells." (PMID 39766901, 2024). "Although not as well characterized as IFIT1/2/3, IFIT5 has also been implicated in the progression of cancer, specifically bladder and prostate cancer." (PMID 36851555, 2023). "At the same time, IFIT5 mRNA levels are significantly elevated in high-grade prostate cancer." (PMID 36544768, 2022). "A recent study has reported that elevated IFIT5 gene expression was correlated with interferon-γ levels in prostate cancer individuals after radiation, and demonstrated that IFN-γ stimulated epithelial-to-mesenchymal transition through the activation of JAK-STAT pathway." (PMID 33008348, 2020). "Our previous study in prostate cancer demonstrated that IFIT5 could negatively regulate the maturation of pre-miR-363, pre-miR-101, and pre-miR-128 that can target EMT transcription factors such as Slug and ZEB14." (PMID 31164632, 2019). "IFIT5 expression was also inversely correlated with miR-363 expression in prostate cancer." (PMID 31921891, 2019). "Our previous studies in prostate cancer and renal carcinoma showed that a interferon induced gene interferon induced protein with tetratricopeptide repeats 5 (IFIT5) acted as an oncogenic gene via promoting EMT4,5, but the role of IFIT5 in bladder cancer is still unknown." (PMID 31164632, 2019).
bladder cancer (7 papers, 2019 to 2023). "Further in vitro testing using bladder cancer cell lines corroborated the analysis of patient samples, with cells overexpressing IFIT5 exhibiting EMT and increased migration." (PMID 36851555, 2023). "In this study, we have identified a new regulatory pathway mediated by IFIT5, which is able to process the stability of suppressor microRNA (miR) in bladder cancer." (PMID 31164632, 2019). "Moreover, the oncogenic role of IFIT5 has been identified in bladder cancer." (PMID 31921891, 2019). "In addition to its functional role in viral RNA degradation, the unique function of IFIT5 in PCa cells is to modulate the turnover of miR subpopulation via recognizing the 5′end specific structure of precursor form; similar observations were found in bladder cancer." (PMID 35908276, 2022). "For example, IFIT5 was shown to promote tumor cell invasion and migration by inducing EMT and downregulating miR-99a in bladder cancer." (PMID 36226166, 2022). "IFIT5 promoted cell invasion and migration by inducing EMT by downregulating miR-99a in bladder cancer." (PMID 31921891, 2019). "When comparing IFIT5 expression levels between nonmuscle-invasive and muscle-invasive bladder cancer samples, the invasive cells exhibited significantly higher levels of IFIT5 expression." (PMID 36851555, 2023). "In prostate and bladder cancer, it was reported that IFIT5 was able to promote epithelial–mesenchymal transition and progression, but there is no study reported in lung cancer, so the role of IFIT5 in lung cancer still needs to be explored." (PMID 36761423, 2022).
renal cell carcinoma (4 papers, 2019 to 2025). "In patients with renal cell carcinoma, IFIT5 expression is significantly higher in primary tumor tissue compared to benign tissues, and elevated levels of IFIT5 mRNA is a predictor of poor overall survival in patients." (PMID 40564154, 2025). "IFNs can enhance renal cell carcinoma invasion via a new mechanism of IFIT5-mediated degradation of tumor suppressor miRNA, promoting EMT." (PMID 40564154, 2025). "For instance, by preventing the transformation of microRNA (miRNA), IFIT5 can increase the expression of EMT transcription factors and increase the risk of developing renal cell carcinoma." (PMID 36532001, 2022). "However, a newly identified mechanism of IFIT5 is regulation of the turnover of tumor suppressor microRNAs (miRNAs), including miR-363 and miR-128, resulting in increased expression of transcription factors of EMT such as slug and ZEB1, thereby enhancing invasion in renal cell carcinoma (RCC)." (PMID 31921891, 2019).
avian influenza (3 papers, 2015 to 2021). Infection of domestic and wild fowl and other birds with influenza A virus. "Overexpression of IFIT5 in transgenic chickens showed significant enhanced resistance to avian influenza and velogenic NDV77." (PMID 34475461, 2021). "Several papers have shown that IFIT5 is very highly expressed in avian influenza infected ducklings." (PMID 25816333, 2015).
breast carcinoma (3 papers, 2023 to 2025). "Researchers identified survival-associated genes that were deregulated in doxorubicin-induced heart failure patients with breast cancer and showed that, in these patients, low levels of IFIT5 expression were associated with shorter DFS." (PMID 40564154, 2025). "The results showed that 17 m7GRGs were risk factors and significantly impacted breast cancer prognosis, whereas NUDT10, NUDT3, EIF4E3, SNUPN, NUDT16, IFIT5 and EIF3D were favourable prognostic factors." (PMID 37353728, 2023). "IFIT5 was proposed to be deregulated by doxorubicin treatment of breast cancer patients." (PMID 40564154, 2025). "Patients with breast cancer who had low levels of expression of the genes CD19, CD79A, IFIT5, MS4A1, and TCL1A had shorter disease-free survival times." (PMID 37684436, 2023).
COVID-19 (3 papers, 2021 to 2023). A disease caused by infection with severe acute respiratory syndrome coronavirus 2. "The most strongly induced significant protein was interferon-induced protein with tetratricopeptide repeats (IFIT) 5 (fold change = 7.65, P = 0.021), consistent with previous reports of a type I interferon signature in neutrophils from COVID-19 patients." (PMID 36622345, 2023). "Both CUN and COV groups, compared with their respective control group, expressed higher level of genes involved in the antiviral response and proliferation, like IFIT5, IFI27 and PIM1, suggesting that those cells could have been activated by SARS-CoV-2 infection." (PMID 35710943, 2022).
glioma (2 papers, 2018 to 2022). A benign or malignant brain and spinal cord tumor that arises from glial cells (astrocytes, oligodendrocytes, ependymal cells). "IFIT5 is expressed in normal glial cells only, and gets upregulated in glioma behaving like a glia cell marker as GFAP." (PMID 29844869, 2018).
influenza (2 papers, 2020 to 2024). An acute viral infection of the respiratory tract, occurring in isolated cases, in epidemics, or in pandemics; it is caused by serologically different strains of viruses (influenzaviruses) designated A, B, and C, has a 3-day incubation period, and usually lasts for 3 to 10 days. "MX1, OASL and IFIT5 genes encode proteins with known functions in influenza defense." (PMID 32381003, 2020). "IFIT5 is upregulated 30-fold in H7N2 influenza-infected avian macrophages and 20-fold in H9N2 influenza-infected chicken macrophage lines." (PMID 39518785, 2024).
malignant melanoma (2 papers, 2022). "The current research describes for the first time that the risk scores created by EIF4E3, LARP1, NCBP3, and IFIT5 can serve as independent prognostic factors for melanoma." (PMID 36473947, 2022). "Studies have reported that high expression of IFIT5 is associated with more immune cell infiltration and its low expression is an independent risk factor for the prognosis of patients with malignant melanoma, which is consistent with the conclusion of this paper." (PMID 36532001, 2022). "To understand the role of m7GMRRGs in melanoma prognosis in further detail, we selected four m7GMRRGs (EIF4E3, LARP1, NCBP3, and IFIT5) to develop prognosis prediction model." (PMID 36473947, 2022).
renal carcinoma (2 papers, 2019 to 2024). A carcinoma arising from the epithelium of the renal parenchyma or the renal pelvis. "Study had also shown that IFIT5 promoted EMT leading to renal cancer invasion." (PMID 38273364, 2024).
acute myeloid leukemia (1 paper, 2025). Acute myeloid leukemia (AML) is a group of neoplasms arising from precursor cells committed to the myeloid cell-line differentiation. "IFIT1, IFIT2, IFIT3, and IFIT5 are overexpressed in acute myeloid leukemia (AML) patients, with higher levels of IFIT2, IFIT3, and IFIT5 predicting poor prognosis." (PMID 41048997, 2025).
autoimmune disease (1 paper, 2020). A disorder resulting from loss of function or tissue destruction of an organ or multiple organs, arising from humoral or cellular immune responses of the individual to their own tissue constituents. "IFIT5, IFI16 and MX2, interferon-stimulated genes, both nuclear transcriptional factors, were found to be upregulated in other autoimmune diseases but not in JDM." (PMID 32110496, 2020).
dengue (1 paper, 2024). "Among the ten strongest predictors of dengue severity, IFIT5, ISG15, and HERC5 were the three most important variables." (PMID 38444851, 2024). "This work provides insights into the NDI and vaccine-induced overlapping immune response and suggests molecular markers (e.g., IFIT5, ISG15, and HERC5) for anti-dengue-specific therapies and effective vaccination development." (PMID 38444851, 2024).
epilepsy (1 paper, 2025). A brain disorder characterized by episodes of abnormally increased neuronal discharge resulting in transient episodes of sensory or motor neurological dysfunction, or psychic dysfunction. "Collectively, these findings point to a potential association between the upregulation of IFIT5 and the incidence of epilepsy, providing valuable insights into the underlying mechanisms of this complex neurological disorder." (PMID 40658715, 2025). "Immunohistochemistry results confirmed that IFIT5 expression was broadly upregulated in the majority of primary epilepsy patient tissue samples, predominantly in neurons." (PMID 40658715, 2025). "This suggests that IFIT5 and its regulatory m7G modification are generally upregulated in epilepsy patients." (PMID 40658715, 2025). "The boxplot revealed that epilepsy patients had up-regulated expression levels of NUDT3, EIF4E3, LARP1, IFIT5, and SNUPN, and down-regulated expression levels of METTL1, EIF4A1, and LSM1." (PMID 40658715, 2025). "Gene expression analysis of datasets GSE143272 and GSE190452 identified 8 differentially expressed m7G regulators (NUDT3, EIF4E3, LARP1, IFIT5, SNUPN, METTL1, EIF4A1, and LSM1) in epilepsy." (PMID 40658715, 2025). "Patients with epilepsy were more likely to exhibit aberrant expression of SNUPN, LSM1, and IFIT5." (PMID 40658715, 2025).